SAMHD1 (SAM and HD domain containing deoxynucleoside triphosphate triphosphohydrolase 1)
Diseases named in the same sentence as SAMHD1 in open-access papers (continued):
Sharing a sentence is not in itself a finding about the gene and the disease.
viral infection (continued). "Our group has reported that SAMHD1 inhibits the nuclear factor kappa-B and IFN-I pathways induced by viral infection and pro-inflammatory stimuli." (PMID 37328105, 2023). "SAMHD1 is transcriptionally downregulated by promoter hypermethylation in lung cancer cells and in CD4 T cells during viral infection." (PMID 35803902, 2022). "In CD4+ myeloid lineage and resting T-cells, SAMHD1 blocks HIV-1 and other viral infections by depletion of the dNTP pool to a level that cannot support replication." (PMID 32576829, 2020). "We show that the TLR3 and RIG-I/MDA5 pathways participate in the regulation of SAMHD1 expression and find that IRF3 phosphorylation and nuclear translocation are critical aspects of SAMHD1 upregulation after IFN-α treatment and virus infection." (PMID 27411355, 2016). "By comparing BMDC from WT and SAMHD1 KO mice we found that murine SAMHD1 blocks HIV-1 and MLV reporter virus infection in primary cells at the level of reverse transcription." (PMID 26667483, 2015). "SAMHD1-mediated HIV-1 restriction occurs via endogenous SAMHD1 depleting the intracellular dNTP pool, thereby inhibiting HIV-1 reverse transcription and viral infection." (PMID 23231760, 2012). "Given that HIV-2/SIV Vpx hijacks the CRL4 (DCAF1) E3 ubiquitin ligase complex to degrade SAMHD1, thereby promoting viral infection, we investigated whether USP37 reverses SIVmac239 Vpx-mediated SAMHD1 degradation." (PMID 39655951, 2025). "SAMHD1 is a regulator of STING-mediated apoptosis in human monocytes, in viral infection." (PMID 39871364, 2025). "Moreover, determination of NTP and dNTP molecules should be conducted to clarify the interactions of viral infections with genes involved in the dNTP metabolism due to the fact that these genes may have other functions not involved in dNTP metabolism, such as viral RNRs and cellular SAMHD1." (PMID 39339888, 2024). "To examine the role of SAMHD1 in inhibiting NF-κB in response to virus infection in dividing and nondividing cells, we infected THP-1 cells with SeV, which is known to efficiently activate NF-κB signaling." (PMID 37100289, 2023). "To examine whether endogenous SAMHD1 and MAVS interact in cells during viral infection, we infected monocytic THP-1 cells with Sendai virus (SeV) for 6 h and then performed IP using SAMHD1 antibodies." (PMID 37328105, 2023). "Thus, SAMHD1 suppresses MAVS activation in response to viral infection, impairs IKKε recruitment to MAVS, and inhibits IKKε phosphorylation upon virus infection." (PMID 37328105, 2023). "In addition, SAMHD1 inhibits the activation of NFκB and type I IFN upon viral infection through direct binding to NFκB as well as IRF7." (PMID 33801276, 2021). "First, because SAMHD1 is preferentially expressed in cells residing within the extrafollicular region of tonsillar explants, where the CD127+ cells are located, we tested the possibility that SAMHD1 was actively restricting viral infection in these cells." (PMID 32353080, 2020). "Our findings reveal that SAMHD1 could be activated by the same signals that trigger type I IFN production, via TLR3 and RIG-I/MDA5 signaling pathways, soon after viral infection." (PMID 27411355, 2016). "In this regard, SAMHD1 has been previously reported to suppress virus infection in resting but not in cycling CD4+ T cells." (PMID 25996507, 2015). "SAMHD1-mediated HIV-1 restriction in myeloid cells and resting CD4+ T-cells is likely a general mechanism to protect host cells from productive viral infection, which can also be a potential strategy of HIV-1 immune evasion to avoid efficient anti-viral innate immunity." (PMID 23092163, 2012). "SAMHD1 alone does not explain some discrepancies between cell type distribution and its ability to restrict viral infection." (PMID 21994799, 2011). "In our patients, SAMHD1 was not expressed when mimicking viral infection in vitro using the Toll-like receptor-3 (TLR3)-agonist Poly(I:C)." (PMID 20842748, 2010).
viral infection (continued). "SAMHD1 is a non-essential gene and has been demonstrated to inhibit viral infection in macrophages, so we hypothesized that SAMHD1 mutant macrophages would be more permissive of lentiviral gene transfer." (PMID 40259927, 2025). "Interestingly, SAMHD1 was one of the restriction factors of the innate immune response identified in this study, which warrants future research on this protein related to SRLV infection and its potential to restrict viral infection." (PMID 34203742, 2021). "Moreover, SAMHD1 KO cells showed an earlier and stronger response to inflammatory stimuli and virus infection compared with THP-1 cells, suggesting that SAMHD1 plays an important role in the balance of innate immune responses to inflammatory stimuli and viral infections." (PMID 37100289, 2023). "The Vpx mutants T17A that did not rescue viral infection and the Q76A mutant that did not bind to DCAF1 were all unable to destabilize SAMHD1." (PMID 23254112, 2012). "As a dGTP-dependent deoxynucleotide triphosphohydrolase, SAMHD1 hydrolyzes intracellular dNTPs and reduces their concentrations to below the levels required for HIV-1 reverse transcription, thereby blocking viral infection in non-cycling myeloid cells." (PMID 23092163, 2012). "However, CDK1 cannot be the sole regulator of SAMHD1 in MDM, as we also observed a modest downregulation of CDK1 protein by IFN-λ, which was not accompanied by significant protection from viral infection." (PMID 29764952, 2018).
leukemia (22 papers, 2013 to 2026). A malignant (clonal) hematologic disorder, involving hematopoietic stem cells and characterized by the presence of primitive or atypical myeloid or lymphoid cells in the bone marrow and the blood. "SAMHD1 mutants selected for the screen include leukemia-associated mutants, R145Q, Y155C, P158S, and R451C, which are located in the allosteric sites of the enzyme." (PMID 34492268, 2021). "Recently, a series of SAMHD1 mutations have been reported in various cancer cells including leukemias, lymphomas, lung cancer, and colon cancer." (PMID 34492268, 2021). "In the future, forodesine may be developed into a precision medicine for a subset of patients with leukemia with acquired SAMHD1 mutations." (PMID 32402273, 2020). "Importantly, our data suggest that forodesine-sensitive leukemias harbor mutations that ablate SAMHD1 expression." (PMID 32402273, 2020). "It was supposed that in leukemias SAMHD1 mutations causing loss of the proteins’ tumor-suppressive function could lead to enhanced drug efficacy." (PMID 29352181, 2018). "SAMHD1 has been suggested to have tumor suppressor activities, as its overexpression can decrease cellular proliferation, and mutation, and loss of SAMHD1 has been reported for several cancers including leukemias, lymphomas, breast, and colorectal cancer." (PMID 29018771, 2017). "A specific R366C/H SAMHD1 mutation has been found in leukaemia and colon cancers, which ablates the dNTP hydrolase activity of SAMHD1 while retaining catalytic-independent functions, and could thus mechanistically contribute to elevated dNTP pools in cancer cells." (PMID 39206868, 2024). "However, it may also be interesting to explore supplementing forodesine with dG in patients with leukemia with acquired SAMHD1 mutations." (PMID 32402273, 2020). "Several studies have reported that high expression of SAMHD1 negatively impacts the efficacy of nucleoside-based chemotherapies in different cohorts of patients with leukemia." (PMID 35978833, 2022). "Here, we investigated the structure and functions of SAMHD1 R366C/H mutants, found in colon cancer and leukemia." (PMID 34492268, 2021). "Although the cytosine analogue CNDAC was anticipated to inhibit SAMHD1, SAMHD1 mediated intrinsic CNDAC resistance in leukaemia cells." (PMID 34641952, 2021). "We therefore propose to use forodesine as a precision medicine for leukemia, stratifying patients by SAMHD1 genotype or expression." (PMID 32402273, 2020). "SAMHD1 expression is downregulated in many cancers, including leukemia, lymphoma, and solid cancers, such as breast and lung cancer." (PMID 26416562, 2015). "This was also observed in human lymphoma/leukemia CD4+ T-cell lines relative to primary CD4+ T-cells that have high endogenous SAMHD1 expression." (PMID 26416562, 2015). "This approach was applied in a recent study characterising the colon cancer and leukaemia‐associated R366C/H mutant, and showed that while this mutation retains noncatalytic roles of SAMHD1, the dNTPase activity is abolished." (PMID 35583750, 2022). "Nevertheless, a potential role of SAMHD1 as a tumor suppressor in AML still needs further investigation, as low SAMHD1 levels in AML bone marrow samples might indicate its role in leukemia induction." (PMID 34480199, 2022). "In this report, we structurally and functionally investigated R366C/H SAMHD1 mutations, found in leukemia and colon cancer, but not in AGS." (PMID 34492268, 2021). "SAMHD1 mediates resistance to anti-cancer nucleoside analogues, including cytarabine, decitabine, and nelarabine that are commonly used for the treatment of leukaemia, through cleavage of their triphosphorylated forms." (PMID 34641952, 2021). "Hence, SAMHD1 inhibitors are promising candidates for the sensitisation of leukaemia cells to nucleoside analogue-based therapy." (PMID 34641952, 2021).
leukemia (continued). "In addition to Myc and Bcl2, other tumor-promoting genes such as Eef2 and Myh10 were upregulated in leukemia cells, whereas tumor suppressors such as Ikzf1, Ikzf2, Arid1b, Arid2, Samhd1, Bach2, and Myo18b were downregulated." (PMID 34907175, 2021). "However, CLL is the most common leukemia in the Western world; thus, significant numbers of patients with CLL have SAMHD1 mutations." (PMID 32402273, 2020). "Moreover, the determination of physiological dNTPs in the presence of CNDAC and combination experiments with the SAMHD1 substrate cytarabine did not provide evidence that CNDAC may function as pharmacological SAMHD1 inhibitor in leukaemia cells." (PMID 34641952, 2021). "SAMHD1 levels may be regulated by SAMHD1 promoter methylation in leukaemia cells." (PMID 32581304, 2020). "Compared to the pronounced effects of SAMHD1 on nelarabine/ AraG activity in ALL, however, SAMHD1 exerted only minor effects on the activity of cytarabine in this leukaemia type." (PMID 32581304, 2020). "Together, our data suggest that SAMHD1 is a biomarker for the stratified use of hypomethylating agents in AML patients and a potential target for the treatment of decitabine-resistant leukemia." (PMID 31375673, 2019). "SAMHD1 downregulation on the mRNA and protein level, compared to CD4+ T-cells from healthy donors or monocytic THP-1 cells, was also observed in various CD4+ T-cell lines derived from leukemia and CTCL patients." (PMID 34480199, 2022). "SAMHD1 is thought to be active in nondividing cells only, which are not infected efficiently by murine leukemia viruses due to their inability to transfer the viral cDNA into the nucleus." (PMID 26667483, 2015).
autoimmune disease (21 papers, 2011 to 2026). A disorder resulting from loss of function or tissue destruction of an organ or multiple organs, arising from humoral or cellular immune responses of the individual to their own tissue constituents. "SAMHD1 is the only deoxynucleotide triphosphohydrolase (dNTPase) in eukaryotes and beyond cancer, it has been linked to other pathological processes, including viral restriction, modulation of immune response and autoimmune diseases." (PMID 37667113, 2024). "Germline mutations in the SAMHD1 gene are associated with development of Aicardi-Goutières syndrome, an autoimmune disease characterized by a type I interferon (IFN-I) dysregulation." (PMID 37328105, 2023). "Mutations in the human SAMHD1 gene cause Aicardi-Goutières (AG) syndrome, an autoimmune disease sharing similar clinical features with systemic lupus erythematosus (SLE)." (PMID 37213666, 2023). "In fact, the SAMHD1 gene is one of the genes that, if mutated, results in the development of the autoimmune disorder, AGS." (PMID 35085552, 2022). "Sterile alpha motif and histidine-aspartic acid domain-containing protein 1 (SAMHD1) is a dNTP triphosphohydrolase involved in the regulation of the intracellular dNTP pool, linked to viral restriction, cancer development and autoimmune disorders." (PMID 32197329, 2020). "Human SAMHD1 mutations can cause a severe autoimmune disorder, suggesting the importance of its dNTPase function in innate immunity." (PMID 26416562, 2015). "Single nucleotide polymorphisms (SNP) in RNASEH2, TREX1 and SAMHD1 genes have been associated with autoimmunity disorders such as AGS and systematic lupus erythematosus." (PMID 22174685, 2011). "From a practical standpoint, our observations suggest several clinical scenarios in which genetic evaluation for SAMHD1 deficiency should be considered in children with seemingly common autoimmune diseases such as juvenile dermatomyositis or systemic lupus erythematosus." (PMID 41496005, 2026). "SAMHD1 was originally identified as being associated with autoimmune diseases." (PMID 38874084, 2024). "Altogether, IFNγ 2, SAMHD1 8 and Klotho 23 have been implicated in autoimmune diseases." (PMID 37213666, 2023). "In addition to its role in the antiviral response, SAMHD1 is also implicated in the autoimmune disease Aicardi–Goutieres syndrome (AGS)." (PMID 29379009, 2018). "The SAMHD1-deficient mouse model could be used as a potential tool to investigate the mechanisms of pathogenic type I IFN responses in autoimmune diseases in humans." (PMID 24257155, 2013). "Additionally, mutations in SAMHD1 are associated with autoimmune disease states, such as AGS8." (PMID 29379009, 2018). "Our findings help define the function of SAMHD1 in antiviral innate immune responses, autoimmune diseases, and inflammation." (PMID 37328105, 2023). "In fact, deficiency in SAMHD1 leads to increased IFN production, upon viral DNA sensing by cGAS, and innate immune activation causing autoimmune disorders in patients." (PMID 30574147, 2018). "Mutations in SAMHD1 that affect its enzyme activity are associated with Aicardi-Goutières syndrome (AGS), an encephalopathic autoimmune disease characterized by symptoms mimicking chronic viral infection." (PMID 29176984, 2017). "Autoimmune diseases like AGS are clearly linked to nucleic acid metabolism since mutations in TREX1, RNASEH2A-2C, SAMHD1, ADAR1, or IFIH1 predispose individuals to disease (12, 48, –, 51)." (PMID 28679751, 2017). "Our results provide insights into the regulation of SAMHD1 activity, thereby facilitating the improvement of HIV mouse models and the development of new therapies for certain cancers and autoimmune diseases." (PMID 29379009, 2018). "The results suggest that SAMHD1 is important for maintaining genome integrity and support the idea of an enhanced replication of endogenous retroelements in the absence of SAMHD1 in vivo, potentially triggering autoimmune diseases like AGS." (PMID 29610582, 2018).
chronic lymphocytic leukemia (18 papers, 2015 to 2026). "In recent years, SAMHD1 mutations were reported in several cancers, such as colorectal cancer, breast cancer and chronic lymphocytic leukemia." (PMID 36578072, 2022). "Although the newly found mutations had no obvious effect on the prognosis of MCL patients, some SAMHD1 mutations previously reported were associated with chronic lymphocytic (B-cell) leukemia development and changed its dNTPase activity." (PMID 34976810, 2021). "Previous studies have identified aberrant SAMHD1 expression as a potential cause of colon cancer, lung cancer, chronic lymphocytic (B-cell) leukemia, and some subtypes of T-cell lymphoma or leukemia." (PMID 34976810, 2021). "Acquired (somatic) SAMHD1 mutations are found in patients with chronic lymphocytic leukemia, CLL (OMIM 151400)." (PMID 32151092, 2020). "Mutations to SAMHD1 have been identified in hypermutated cancers, and germline mutation to SAMHD1 can cause Chronic Lymphocytic Leukaemia and auto-immune condition Aicardi–Goutières Syndrome." (PMID 31296733, 2019). "Additionally, recurrent SAMHD1 mutations have been found in a variety of haematological malignancies, such as chronic lymphocytic leukaemia (CLL), T-cell prolymphocytic leukaemia and mantle cell lymphoma." (PMID 39206868, 2024). "As an important regulator of cell proliferation and a key player in dNTP homeostasis, mutations to SAMHD1 are implicated in hypermutated cancers, and germline mutations are associated with Chronic Lymphocytic Leukaemia and the inflammatory disorder Aicardi–Goutières Syndrome." (PMID 31296733, 2019). "Moreover, SAMHD1 is frequently mutated in a variety of cancer types, such as chronic lymphocytic leukemia (CLL) and colorectal cancer." (PMID 29884836, 2018). "In particular, SAMHD1 has been found mutated in chronic lymphocytic leukemia (CLL)." (PMID 26606981, 2015). "Indeed, downregulation or recurrent SAMHD1 mutations were found in some cancer entities like chronic lymphocytic leukemia, colon cancer and T-cell prolymphocytic leukemia and were particular increased in chemorefractory cases, which classifies SAMHD1 as cancer gene." (PMID 33591315, 2021). "Furthermore, SAMHD1 mutations could be a founder event in chronic lymphocytic (B-cell) leukemia, and its potential role in cancer pathogenesis has been investigated." (PMID 34976810, 2021). "Moreover, mutations may affect SAMHD1 function, as demonstrated in patients with chronic lymphocytic leukaemia and colorectal cancer." (PMID 32581304, 2020). "While one AGS patient with biallelic SAMHD1 GVs and chronic lymphocytic leukemia has been described, heterozygous GVs in SAMHD1 have been detected in a multiple myeloma family and significantly associated with prostate cancer risk." (PMID 41546701, 2026). "This agrees with previous reports of downregulated SAMHD1 expression in chronic lymphocytic leukemia, cutaneous T-cell lymphoma, and lung adenocarcinoma." (PMID 33857133, 2021). "Alternately, homozygous deletion of RNASEH2B has been shown to occur in chronic lymphocytic leukemia (CLL) and other malignancies, Similarly, pathogenic mutations in SAMHD1 have been reported in up to 11% of CLL patients." (PMID 33717156, 2021). "SAMHD1 is frequently mutated not only in AGS but also in a variety of human cancers, such as chronic lymphocytic leukemia, colorectal cancer, and epidermotropic cutaneous T-cell lymphoma." (PMID 33857133, 2021). "Additionally, the role of SAMHD1 in numerous types of cancer, such as chronic lymphocytic leukemia, lung cancer, and colorectal cancer, has been extensively studied." (PMID 35978833, 2022). "Due to its role in DSBR, it is conceivable that mutations in the SAMHD1 gene, as well as silencing hypermethylation of the SAMHD1 promoter, might play a role in tumorigenesis of various forms of cancer such as colon cancer, chronic lymphocytic leukemia, and lung adenocarcinoma." (PMID 33801276, 2021).
chronic lymphocytic leukemia (continued). "Cancers, such as chronic lymphocytic leukemia (CLL), lung cancer, cutaneous T cell lymphoma (CTCL), acute myeloid leukemia, and colon cancer, are characterized by the downregulation of SAMHD1." (PMID 32244340, 2020).